PTPN22 (protein tyrosine phosphatase non-receptor type 22)
Diseases named in the same sentence as PTPN22 in open-access papers (continued):
Sharing a sentence is not in itself a finding about the gene and the disease.
rheumatoid arthritis (continued). "The PTPN22 allele C1858T has a single amino acid substitution R620W (arginine to tryptophan; rs2476601, OR= 1.890), and has been associated with T1D, Hashimoto’s thyroiditis, rheumatoid arthritis (RA), systemic lupus erythematosus (SLE), vitiligo and Graves disease." (PMID 35603161, 2022). "The PTPN22 was selectively expressed in immune-related tissues (i.e., lymphocytes cells and spleen), and there are over 100 papers of PubMed database co-mentioning the gene and rheumatoid arthritis in the titles or abstracts." (PMID 31694669, 2019). "Additionally, differences in PTPN22 isoform ratios have been reported in patients with rheumatoid arthritis and systemic lupus erythematosus." (PMID 30483260, 2018). "Several protein tyrosine phosphatase non-receptor 22 (PTPN22) single-nucleotide polymorphisms (SNPs) have been significantly related with rheumatoid arthritis (RA) susceptibility." (PMID 28874816, 2017). "PTPN22 1858C>T gene polymorphism is the best genetic risk factor so far documented, independent of HLA, a for rheumatoid arthritis." (PMID 24985973, 2014). "The results obtained by different studies support the association of the PTPN22 1858T allele with sporadic childhood-onset systemic lupus erythematosus (SLE) in the Mexican population, and susceptibility to rheumatoid arthritis in the Western Mexican population." (PMID 25289035, 2014). "In addition, how the overall activity of PTPN22 is regulated and how the R-to-W conversion contributes to rheumatoid arthritis is still poorly understood." (PMID 22427951, 2012). "To test this hypothesis, we opted to examine the transcript level of PTPN22 isoforms in whole peripheral blood of patients from the Brigham and Women's Hospital Rheumatoid Arthritis Sequential Study (BRASS) cohort." (PMID 22427951, 2012). "The R620W variant in protein tyrosine phosphatase non-receptor 22 (PTPN22) is associated with rheumatoid arthritis (RA)." (PMID 22264340, 2012). "PTPN22, PADI-4, and CTLA-4 have been associated with risk for rheumatoid arthritis (RA)." (PMID 18462498, 2008). "In the present paper, we used the North American Rheumatoid Arthritis Consortium data provided for Genetic Analysis Workshop 15 Problem 2 to: 1) estimate the penetrances of PTPN22 and HLA-DRB1 and, 2) test the selected model of PTPN22 conditional on the rheumatoid factor status." (PMID 18466483, 2007). "As indicated by Begovich and colleagues, the chromosome 1 linkage suggestion observed in the ASP analysis of the North American Rheumatoid Arthritis Consortium genome scan is not explained by the findings of the PTPN22 association." (PMID 16277672, 2005). "Additionally, the C1858T PTPN22 polymorphism associated with alopecia areata was shown to be directly linked with the inability of PTPN22 to suppress PADI4 activity, and enhance inflammation-stimulated NET formation in rheumatoid arthritis." (PMID 34966743, 2021). "Good examples of known shared risk loci in IMDs are PTPN22, IL23R and TNFAIP3, which have allowed the repositioning of anti-TNF and anti-IL-12/IL-23 therapies to be used in rheumatoid arthritis (RA) and systemic lupus erythematosus (SLE), among others." (PMID 33317201, 2020). "At the same time, some are typically related to other autoimmune diseases as diabetes or rheumatoid arthritis (RA) (PTPN22 and STAT4)." (PMID 28350323, 2017). "In rheumatoid arthritis (RA), another SNP in PTPN22 gene, a G-C substitution (rs2488457) in the promoter, had been addressed as a risk factor in several studies." (PMID 25781893, 2015). "Genome-wide association studies revealed that variants within the gene locus encoding for protein tyrosine phosphatase non-receptor type 22 (PTPN22) are linked with the risk to develop autoimmune disorders, including rheumatoid arthritis, type 1 diabetes, UC and CD." (PMID 23991106, 2013).
rheumatoid arthritis (continued). "A C-to-T single nucleotide polymorphism (SNP) located at position 1858 of human PTPN22 cDNA and converting an arginine (R620) to tryptophan (W620) confers the highest risk of rheumatoid arthritis among non-HLA genetic variations that are known to be associated with this disease." (PMID 22427951, 2012). "The genes PTPN22 and HLA-DRB1 have been found by a number of studies to confer an increased risk for rheumatoid arthritis (RA), which indicates that both genes play an important role in RA etiology." (PMID 20017999, 2009). "These include PTPN22, associated with systemic lupus erythematosus (SLE), rheumatoid arthritis (RA), T1D, and Graves' Disease (GD), STAT4, associated with SLE and RA, and the IL7R and KIAA0350 gene regions, which are shared between T1D and MS." (PMID 19119414, 2009). "The genetic contribution to rheumatoid arthritis (RA) susceptibility is undisputed, with replicated associations identified with haplotypes of the HLA-DRB1 locus and SNPs in PTPN22." (PMID 20018087, 2009). "In order to model the effect of PTPN22 on rheumatoid arthritis (RA), we determined the combination of single-nucleotide-polymorphisms (SNPs) showing the strongest association with RA." (PMID 18466535, 2007). "The linkage proof is so far lacking, however, as the linkage analysis of the North American Rheumatoid Arthritis Consortium RA-affected sib-pairs resource for this PTPN22 SNP was inconclusive." (PMID 16277672, 2005). "Thus, PTPN22 could be a potential therapeutic target for rheumatoid arthritis." (PMID 39483464, 2024). "For instance, PTPN22, known as one the strongest risk gene to promote the development of ADs, is particularly related to systemic lupus erythematosus (SLE), rheumatoid arthritis (RA), and type 1 diabetes (T1D)." (PMID 38259487, 2023). "The PTPN22 acts as a negative regulator of T cell receptor (TCR), which has been suggested contributing to rheumatoid arthritis by many papers." (PMID 31694669, 2019). "The C1858T polymorphism within the protein tyrosine phosphatase PTPN22 (encoding PTPN22R620W) is a major risk factor for the development of multiple autoimmune diseases, including rheumatoid arthritis (RA), type I diabetes, lupus and juvenile idiopathic arthritis (JIA)." (PMID 29040339, 2017). "The PTPN22 rs2476601 polymorphism is associated with rheumatoid arthritis (RA); nonetheless, the association is weaker or absent in some southern European populations." (PMID 21949702, 2011). "For a few chosen autoimmune disorder receptors (protein tyrosine phosphatase, nonreceptor type 22 (lymphoid) isoform 1 (PTPN22), type 1 diabetes, rheumatoid arthritis, and SARS-CoV-2 Mpro, the optimal binding characteristics of the compounds were described." (PMID 37771457, 2023). "Protein tyrosine phosphatase nonreceptor type 22 (PTPN22), an intracellular nonreceptor-like protein tyrosine phosphatase, is involved in several chronic inflammatory diseases, including rheumatoid arthritis and diabetes." (PMID 37443055, 2023). "Based on findings concerning PTPN22, they suggest that multiple sclerosis (MS) may have a pathogenesis that is distinct from SLE, rheumatoid arthritis (RA) and type 1 diabetes (T1D)." (PMID 22174698, 2011). "Testing genetic models of rheumatoid arthritis that include the PTPN22 SNP in addition to the HLA-DRB1 locus did not affect the results, nor did subgroup analysis of PTPN22 conditional on the rheumatoid factor status." (PMID 18466483, 2007). "Many genes contribute to increase the susceptibility to rheumatoid arthritis, including human leukocyte antigen (HLA) (such as HLA-DRB1) coding genes and non-HLA coding genes (such as Protein tyrosine phosphatase non-receptor type 22 (PTPN22), Peptidylarginine deiminase 4 (PADI4))." (PMID 35246023, 2022). "ELISA is not a substitute for PCR in directly genotyping PTPN22 or PADI4, but it is useful in rheumatoid arthritis (RA) research." (PMID 40983977, 2025).
rheumatoid arthritis (continued). "Established loci for rheumatoid arthritis (RA), including HLA-DRB1 and PTPN22, do not fully account for the genetic component of susceptibility to the disease." (PMID 20017998, 2009).
Autoimmunity (115 papers, 2007 to 2026). The occurrence of an immune reaction against the organism's own cells or tissues. "A R620W polymorphism (C1858T) in the P1 motif of PTPN22 has emerged as a major autoimmunity risk factor, and a strong association between PTPN22 R620W and SLE has been reported by many studies." (PMID 40911684, 2025). "Still, our understanding of the effect of the autoimmunity-associated allelic variant of Ptpn22 (PEP-R619W) on antiviral immunity remains incomplete, as previous reports have only focused on chronic Lymphocytic Choriomeningitis virus (LCMV) infection." (PMID 40791464, 2025). "Changes in T-cell receptor signaling linked to PTPN22 polymorphisms have the potential to exacerbate autoimmunity and reduce immunological tolerance." (PMID 40321894, 2025). "The PTPN22 1858C>T allele is strongly associated with the development of autoimmunity, but the murine equivalent mutation has also been shown to be protective during viral infection and cancer." (PMID 41208109, 2025). "Beyond the HLA region, the PTPN22 gene has emerged as one of the strongest genetic risk factors for the development of autoimmunity." (PMID 40238817, 2025). "The results of this research define new mechanisms by which the autoimmunity-associated allele of PTPN22 augments innate antiviral immunity and enhances protection against coronavirus infection." (PMID 40791464, 2025). "Following the identification of PTPN22 R620W as a risk factor for autoimmunity, several studies have assessed its association with immune responses to infection." (PMID 39039893, 2024). "The R620W SNP variant in PTPN22, through altered phosphatase activity, disrupts T-cell activation, contributing to autoimmunity and the progression of these diseases." (PMID 38675400, 2024). "The strong genetic link between the PTPN22 minor allele (R620W) and autoimmunity would be expected to be an evolutionary disadvantage." (PMID 38512979, 2024). "Although research has been done to define how this allele potentiates autoimmunity, the influence PTPN22 and its pro-autoimmune allele has in anti-viral immunity remains poorly defined." (PMID 38512979, 2024). "It is likely that effects on T cells, B cells, myeloid cells and granulocytes all contribute to autoimmunity phenotypes associated with expression of PTPN22 R620W." (PMID 39039893, 2024). "Our data suggest that the presence of the Ptpn22 autoimmunity associated allele affects multiple parts of the anti-viral immune response critical for controlling a chronic infection." (PMID 38512979, 2024). "PTPN22 and its alternative allele, 1858C>T, has largely been studied in the context of autoimmunity." (PMID 38512979, 2024). "Taken together, these observations suggest that PTPN22 contributes to autoimmunity by establishing temporal windows of risk for specific diseases that coincide with periods of altered T cell responsiveness." (PMID 36961507, 2023). "As in the whole cohort, PTPN22 demonstrated the strongest association with the development of autoimmunity in the subgroup, with IAA as the first AAB." (PMID 35812428, 2022). "In T and B cells, PTPN22 regulates antigen receptor signaling, making it a major focus of studies investigating its role in autoimmunity risk." (PMID 35979360, 2022). "Csk H21I and K43D will be useful tools for dissecting the protein-specific drivers of autoimmunity mediated by the human polymorphism PTPN22 R620W, which impairs interaction with Csk and with the E3 ubiquitin ligase TRAF3." (PMID 35393453, 2022). "The C1858T variant of the protein tyrosine phosphatase N22 (PTPN22) gene is associated with pathophysiological phenotypes in several autoimmune conditions, namely, Type 1 diabetes and autoimmune thyroiditis." (PMID 35355982, 2022). "In this review we will discuss the known functions of PTPN22 in human cells, and we will elaborate on how autoimmunity-associated variants influence these functions across the panoply of immune cells that express PTPN22." (PMID 33717184, 2021).
Autoimmunity (continued). "PTPN22-C1858T is the most talked about single-nucleotide polymorphism (SNP) in the field of autoimmunity; this SNP causes R620W substitution in PTPN22 gene’s C-terminal region." (PMID 33717071, 2021). "Currently, the role of the PTPN22 C1858T polymorphism in autoimmunity is suggested to be alteration of both the innate and adaptive immune responses." (PMID 33746952, 2021). "In contrast, an autoimmunity-associated PTPN22 variant (V619W) that leads to increased PTPN22 function causes increased NLRP3 inflammasome activation and excess IL-1β production that protects mice from experimental colitis." (PMID 33808793, 2021). "More recently, the core function of PTPN22 as well as functional derangements imparted by the autoimmunity-associated variant allele of PTPN22 have been examined in monocytes, macrophages, dendritic cells, and neutrophils." (PMID 33717184, 2021). "Autoimmunity-related risk variants in protein tyrosine phosphatase non-receptor type 22 (PTPN22) and cytotoxic T lymphocyte associated protein 4 (CTLA4) genes were found to be associated with infection-triggered ME/CFS in a recent study." (PMID 33889154, 2021). "HLA alleles (DRB1*0101 and DRB1*0404) and the PTPN22 rs2476601 (R620W) locus were associated with autoimmunity, while variants in IFIH1, PTPN22, SH2B3, BACH2 and CTLA4 were associated with occurrence of multiple autoantibodies." (PMID 32797243, 2020). "WES revealed heterozygous carrier status of the PTPN22 mutation R620W, which is associated with an increased risk for autoimmunity." (PMID 33408719, 2020). "We found a significantly increased frequency of the PTPN22 rs2476601 risk allele A, that confers susceptibility to autoimmunity, in ME/CFS patients (allele frequency (AF) 12%, odds ratio (OR) 1.50, p = 0.033) compared to healthy controls (AF 8%, n = 201)." (PMID 32328064, 2020). "We aimed to provide an overview to interpret the reported significant findings and discuss the genetic association of autoimmunity with the PTPN22 1858 C/T polymorphism." (PMID 30871019, 2019). "In this review, we have synthesized all available data reporting the association of the PTPN22 1858 C/T polymorphism with autoimmunity retrieved from meta-analyses." (PMID 30871019, 2019). "A meta-analysis of the combined datasets revealed an estimated increase of 0.514% in the frequency of Tregs in circulation per copy of the autoimmunity associated PTPN22 Trp620 allele (SE = 9.2 × 10−3, Pcombined = 3.2 × 10−6)." (PMID 31781109, 2019). "While there are additional PTPn22 risk alleles that are associated with increased risk of autoimmunity, we will focus on the more understood R620W allele." (PMID 29681901, 2018). "PTPN22 is described as the hallmark autoimmunity gene, and one specific single nucleotide polymorphism (SNP), rs2476601, is associated with multiple autoimmune diseases, impaired T cell regulation, and autoantibody formation." (PMID 30705675, 2018). "Given the reported associations between autoimmunity and outcome after LTx we assessed the relation of the PTPN22 risk variant in both patients and donors and the incidence of chronic rejection after LTx." (PMID 30705675, 2018). "Alleles of genes that encode or regulate expression of components of this axis, including SHIP-1, SHP-1, Csk/PTPn22, and Lyn, have been shown to confer risk of autoimmunity." (PMID 29681901, 2018). "PTPN22 C1858T mutation encoding for the R620W lymphoid tyrosine phosphatase variant, plays a potential pathophysiological role in autoimmunity." (PMID 28437437, 2017). "Conversely, IBD patients who carry an autoimmunity-associated PTPN22 variant have increased IL-1β levels." (PMID 28561062, 2017). "We reason that in future studies, by restricting loss of PTPN22 to tumor-specific T cells, undesirable autoimmunity will be minimized." (PMID 29116089, 2017).
Autoimmunity (continued). "Previous studies identified an inherited human coding variant (PTPN22-R620W), associated with an increased likelihood of autoimmunity and susceptibility to pathogens such as Mycobacterium tuberculosis." (PMID 28522807, 2017). "The rs6679677 (PHTF1-PTPN22) is reported as a susceptibility factor for autoimmunity in diabetes type 1 while PTPN22 is a well-known RA risk gene." (PMID 27898717, 2016). "An association of PTPN22 dysfunction with autoimmunity fits well with the known roles of phosphatases in attenuating signaling pathways integral to immune cellular reactivity." (PMID 27288531, 2016). "The precise function of PTPN22 and how the variant protein contributes to autoimmunity is not well understood." (PMID 27288531, 2016). "PTPN22 C1858T SNP, which results in R620W substitution in the encoded protein, creates diabetes-specific autoimmunity." (PMID 26734582, 2015). "Variants of the gene PTPN22 have been shown to lead to a predisposition of autoimmunity by effecting the removal of auto-reactive T-cells." (PMID 20018088, 2009). "This underlines the importance of the pathway controlled by PTPN22 in autoimmunity, but indicates distinct regulatory changes in the pathway are involved in different disease states." (PMID 19951419, 2009). "In conclusion, our results indicate that the autoimmunity-associated allele of PTPN22 enhances innate antiviral immunity against acute murine coronavirus infection, MHV A59, and adds to the growing literature supporting the protective role of this allele during viral and tumorigenic challenges." (PMID 40791464, 2025). "It should be emphasized that disease-associated PTPN22 polymorphisms will affect the function of many leukocyte lineages in addition to T cells that may influence onset the autoimmunity." (PMID 39039893, 2024). "Thus, it was of interest to assess the impact of the PTPN22 autoimmunity associated allele has during virus infection." (PMID 38512979, 2024). "The autoimmunity predisposing PTPN22 is a gain-of-function mutant suggesting that a specific small-molecule inhibitor could eliminate its effect." (PMID 37771457, 2023). "It is also possible that a secondary effect of the autoimmunity risk allele PTPN22 R620W could be to increase Csk homodimer formation via loss of PTPN22 competition for SH3-domain access." (PMID 35393453, 2022). "This strongly reflects the association of PTPN22 SNPs with autoimmunity." (PMID 36013501, 2022). "We found that the C129S mutation in Ptpn22 leads to reduced catalytic activity and increased susceptibility to oxidative inactivation in vitro, causing concomitant upregulation of T cell activation and T-cell-mediated autoimmunity in a NOX2-dependent manner." (PMID 35587260, 2022). "Although the exact mechanism by which the R620W variant predisposes to autoimmunity remains largely unknown, PTPN22 with a tryptophan residue at position 620 (Trp620) binds Csk less efficiently than the variant with an arginine at this position." (PMID 33746952, 2021). "The autoimmunity-associated PTPN22 variant promotes NLRP3 activity, caspase-1 activation, and secretion of IL-1β and IL18, which might—at least partially—explain the pro-inflammatory character of this PTPN22 variant in T1D, RA and SLE development." (PMID 32751912, 2020). "In this study we tested the hypothesis that a gene, PTPN22, identified as a risk factor for autoimmunity might increase susceptibility to development of autoimmune conditions following lymphodepletion." (PMID 32047502, 2020). "On the contrary, the autoimmunity-associated PTPN22 variant enhanced IL-1β secretion." (PMID 32751912, 2020). "PTPn22 variants are among the risk alleles most strongly linked to human autoimmunity, but the molecular mechanism of PTPn22 action and consequence of risk allele defect(s) remains unclear." (PMID 29681901, 2018).